USP22 (ubiquitin specific peptidase 22)
Diseases named in the same sentence as USP22 in open-access papers (continued):
Sharing a sentence is not in itself a finding about the gene and the disease.
cancer (continued). "In the current work, we present a broad role of USP22 in supporting the OXPHOS-activity in several cancer entities including the most aggressive forms of BC (TNBC, HER2+-BC)." (PMID 38347585, 2024). "Efforts have been made to develop and improve USP22 inhibitors to treat cancers by inhibiting its functions." (PMID 38784391, 2024). "Since its discovery as being strongly associated with poor patient survival in numerous malignancies, USP22 was reported to indeed possess a pro-tumorigenic function in various cancer models." (PMID 38347585, 2024). "The pro-cancer mechanisms of USP22 involve multiple aspects such as glycolysis, immune microenvironment, lipid metabolism, oxidative phosphorylation, and angiogenesis." (PMID 38784391, 2024). "USP22 is not only indicative of aggressive cancer types but also actively contributes to cancer progression." (PMID 38474186, 2024). "Ubiquitin‐specific protease 22 (USP22) is an ubiquitin‐specific protease that has been demonstrated to have potent carcinogenic effects on a variety of cancers and is involved in several biological processes." (PMID 39661501, 2024). "In alignment, our findings showed that USP22-depletion dramatically enhanced cancer cell drug response to standard therapies as well as to complex I and complex V inhibitors." (PMID 38347585, 2024). "Given that several cancer entities become more dependent on OXPHOS following targeted therapies, USP22 should be considered a valuable therapeutic target to combat these aggressive properties in cancer patients." (PMID 38347585, 2024). "The depletion of USP22 in cancer models leads to reduced tumor growth and increased T-cell cytotoxicity." (PMID 38474186, 2024). "USP22 stabilizes c-Myc and enhances its transcriptional activity through deubiquitination of c-Myc in cancer cells." (PMID 37946202, 2023). "SiRNA-mediated knockdown of USP7 significantly suppressed the parental A549 and H1299 cancer cells, and further suppressed the USP22-Ko A549 and H1299 cells." (PMID 37946202, 2023). "In summary, in this study, we have identified a “feedback” of upregulation of USP22 upon USP7 inhibition in cancer cells." (PMID 37946202, 2023). "The function of Usp22 has been investigated in multiple cancer cell lines; these studies showed that the activation of Usp22 due to its overexpression tended to promote cell survival pathways and inhibit apoptosis." (PMID 37896966, 2023). "USP22 maintains XPC (nucleotide excision repair protein) stability through deubiquitylation to promote cancer cells survival to DNA damage." (PMID 36906615, 2023). "In cancers, USP22 is possibly capable of reprogramming the TME and influence the response to immunotherapy." (PMID 37658402, 2023). "Collectively, our study identifies the USP22-FoxM1-integrin β1 signaling axis critical for cancer stemness and offers a potential target for antitumor therapy." (PMID 37398311, 2023). "USP7 inhibitor treatment further suppresses in vivo angiogenesis and tumor growth and induced more apoptosis in USP22-Ko cancer xenografts." (PMID 37946202, 2023). "In the study, we found that targeting USP7 via either siRNA-mediated knockdown or pharmaceutical inhibitors dramatically upregulates USP22 in cancer cells." (PMID 37946202, 2023). "H2Bub1 is a well-known key target of USP22 in cancer cells, and it is involved in histone modification and gene expression; loss of H2Bub1 is frequently observed in and associated with more malignant phenotype and poor prognosis of various cancers." (PMID 37946202, 2023). "More recent studies have shown a correlation between the overexpression of Usp22 and poor survival rates, the occurrence of metastases, and resistance to therapy with frequent recurrence of various types of cancer." (PMID 37896966, 2023).
cancer (continued). "Recent studies also demonstrate that USP22 plays a critical role in cancer immunosuppression through stabilizing FOXP3 activity in Treg and programmed death-ligand 1 (PD-L1) in cancer." (PMID 37946202, 2023). "USP22 is considered a putative cancer stem cell (CSC) marker which is critical for CSCs self-renewal in varous cancers, and a proangiogenic factor in the placental labyrinth." (PMID 37946202, 2023). "To further test this, we generated in vivo xenograft tumors of the parental and USP22-Ko A549 cancer cells in mouse, and then the xenografts were treated with a USP7-specific inhibitor P5091 at the previously reported concentration." (PMID 37946202, 2023). "In particular, in samples derived from solid cancers, aberrant expression of Usp22 was documented as providing T cell exhaustion and allowing evasion from the immune system, leading to cancer progression." (PMID 37896966, 2023). "Semi-quantitative IHC analysis indicated that Ki67-positive cells were significantly lower, while cleaved caspase 3-positively stained area/cells were significantly higher in USP22-KO A549 cancer tissues than the parental A549 cancer tissues." (PMID 37946202, 2023). "USP22 accelerates necroptotic cell death in several cancer cells via regulating RIPK3 ubiquitination." (PMID 36906615, 2023). "As expected, USP22 deletion dramatically inhibited 4T1 cancer colonization to the lung by reducing more than 60% of tumor nodules with further reduced metastatic foci size." (PMID 37398311, 2023). "By Western blot analysis, we showed that MDM2 was slightly decreased in both parental and USP22-Ko A549 cancer cells, while USP22 was significantly upregulated by P5091 treatment, which confirms that P5091 effectively inhibited USP7 deubiquitinase activity." (PMID 37946202, 2023). "Recent studies have focused on identifying USP22 substrates, which have helped shed light on the involvement of USP22 in cancer initiation and progression." (PMID 38045832, 2023). "USP22 has been suggested as a cancer stem cell gene or death-from cancer signature gene and its high expression often predicts the poor clinical outcomes of cancer patients 7, but its role in maintaining CSC stemness remains to be defined." (PMID 37398311, 2023). "Overall, these data showed that MDM2 inhibitor enhanced the antipancreatic cancer effects of USP22 overexpression in vitro and in vivo." (PMID 34743406, 2022). "Considering the critical role of c-Myc oncogene in cancer, we herein further investigated the impact of c-Myc on USP22-promoter-driven luciferase activity using an additional siRNA to knock down c-Myc in H1299 cancer cells." (PMID 36123698, 2022). "As a de‐ubiquitination‐related molecule, USP22 suppresses cancer progression by inhibiting the degradation of various proteins." (PMID 34743406, 2022). "Recently, several micro RNAs (miRNAs) have been reported to inhibit the expression of USP22 in cancers." (PMID 36123698, 2022). "High USP22 expression levels occur in various cancers and have the potential application as predictive or prognostic markers." (PMID 35203285, 2022). "The USP22 gene is located on short arm of the chromosome 17p11 and plays an important role in developmental and cancer biology through both histone ubiquitination dependent and independent pathways." (PMID 36123698, 2022). "In summary, USP22 downregulation reduces cancer cell proliferation, migration, and invasion and reduces tumor growth and metastasis in vivo." (PMID 35935969, 2022). "USP22 has been reported to be a cancer signature gene and is highly expressed in a variety of cancers." (PMID 35449157, 2022).
cancer (continued). "USP22 is also considered a putative cancer stem cells (CSCs) marker in varous cancers, while CSCs are known for therapy resistance and recurrence in cancers." (PMID 36123698, 2022). "SIRT1 was previously reported to be an important mediator of USP22-driven cancer resistance, promotes HCC cell proliferation, and enhances resistance to chemotherapy." (PMID 35935969, 2022). "HIF-1α knock-down resulted in the abrogation of the USP22-enhanced cancer stemness and glycolysis under hypoxic conditions." (PMID 36497394, 2022). "Based on the high evolutionary conservation from yeast to humans we wanted to analyze the localization of Usp22, the ortholog of Ubp8, which is a cancer signature gene overexpressed in aggressive GBM with poor prognosis." (PMID 35626719, 2022). "Starting from yeast and our findings on the role of Ubp8 in hypoxia, we extended our analysis to the human ortholog and signature cancer gene Usp22 in glioblastoma tumor specimens." (PMID 35626719, 2022). "Of late, KCNQ1OT1 was observed to support ubiquitin-specific peptidase 22 (USP22)-mediated stabilization of PD-L1 by deactivating miR-30a-5p and thereby inhibiting the anti-cancer immunity of CD8+ T cells." (PMID 35055115, 2022). "Usp22 overexpression is observed in several human cancers and is correlated with poor patient outcomes." (PMID 34503086, 2021). "USP22 can exert its cancer-promoting effect by upregulating the nicotinamide phosphoribosyltransferase (NAMPT)/SIRT1, AKT and ERK signaling pathways involved with c-Myc activation." (PMID 34179009, 2021). "Further research is needed to clarify the multifaceted role of USP22 in cancer and, importantly, to identify which tumor types or subgroups will benefit from USP22 inhibition." (PMID 33920268, 2021). "A systematic analysis of the protein levels of all the subunits of the DUB module in different human cancers is necessary in order to understand the molecular impact of Usp22 overexpression in tumorigenesis." (PMID 34503086, 2021). "Because of its reported association with tumor aggressiveness and progression of numerous cancers, USP22 has been the focus of increasing research efforts in recent years." (PMID 34007022, 2021). "Collectively, these patient-derived data are in agreement with USP22 deletion and diminished expression being pathogenic events driving cancer progression via aberrant H2Bub1 regulation and CIN in multiple cancer types." (PMID 33801331, 2021). "The oncogenic role of USP22 involves the suppression of apoptosis in cancer cell lines by modulating various substrates." (PMID 33919439, 2021). "USP22 was identified as a member of the so-called “death-from-cancer” signature predicting therapy failure in cancer patients." (PMID 34007022, 2021). "Based on the upregulation of USP22 expression in cancers, the induction of necroptosis can be an effective clinical strategy to kill cancer cells with the active USP22/SIRT1 axis, which inhibits apoptosis." (PMID 33919439, 2021). "Other studies suggest that USP22 overexpression induces enhanced resistance to apoptosis and treatment resistance in multiple cancer cell lines." (PMID 33369872, 2021). "As USP22 deletions occur frequently and are associated with reduced patient survival in multiple cancer types, this study indicates that reduced USP22 expression and aberrant H2Bub1 regulation in tumors may drive genetic heterogeneity and promote cancer pathogenesis." (PMID 33801331, 2021). "The context-specific outcomes of altered Usp22 expression in cancer cell lines and mouse models highlight the need to define Usp22 functions in normal cells and processes." (PMID 34503086, 2021). "Accordingly, USP22 was considered a promising therapeutic target in cancer and efforts are underway to generate and optimize USP22 inhibitors." (PMID 33920268, 2021).
cancer (continued). "In this study, we examined the functional impact reduced USP22 expression (i.e., H2Bub1 abundance) has on chromosome structure and mitotic fidelity and gained clinical insight into its potential implications in cancer." (PMID 33801331, 2021). "USP22 has been involved in a plethora of physiological and pathophysiological activities, as cell cycle regulation, anti-apoptosis and cancer development." (PMID 34226501, 2021). "This possibility is further buttressed by patient survival curves showing that USP22 deletions correspond with worse survival in numerous cancer types." (PMID 33801331, 2021). "USP22 was thought to have a cancer-promoting effect, and its gene was confirmed as one of 11 genes called “death-from-cancer”." (PMID 34179009, 2021). "A positive correlation between USP22 expression and cancer disease progression has been frequently reported in the past." (PMID 34007022, 2021). "Ubiquitin-Specific Protease 22 (USP22) was identified as a member of the so-called “death-from-cancer” signature predicting therapy failure in cancer patients." (PMID 34943954, 2021). "In osteosarcoma cells, overexpression of USP22 leads to increased activity of the PI3K/Akt pathway and causes cancer." (PMID 33498168, 2021). "Usp22 regulates histone H2B monoubiquitination and exhibits both oncogenic and tumor-suppressor roles in cancer." (PMID 35116051, 2021). "USP22 was initially identified in microarray screens as a member of an 11-gene “death-from cancer” signature that can be used to predict tumor recurrence, metastasis, highly aggressive tumors, and poor prognosis for people with one of several types of cancers." (PMID 32616828, 2020). "USP22 was regarded as an oncogene because it is overexpressed in malignant tumors of several tissues." (PMID 32665011, 2020). "Despite numerous previous studies on the roles of USP22 in cancer, the effectors and signaling pathways downstream of USP22 are not fully understood." (PMID 32063746, 2020). "Gene set enrichment analysis (GSEA) showed that cancer-related pathways were significantly enriched in USP22-KD H1975 cells." (PMID 32294625, 2020). "Overall, the evidence indicates that overexpression of USP22 in cancer leads to the abnormal activation of several pathways involved in cell survival and tumorigenesis." (PMID 32616828, 2020). "Another remarkable subunit of SAGA that appears to be highly engaged in cancer is USP22, which is the catalytic subunit of DUBm." (PMID 32616828, 2020). "Taken together, our results indicated that USP22 participated in proteasome degradation of PD-L1 in human cancer cells." (PMID 32665011, 2020). "Although previous studies have extensively reported USP22 overexpression and its oncogenic role in cancer, recent studies suggest USP22 downregulation and tumor suppressor properties in some cancers." (PMID 32063746, 2020). "The oncogenic role of USP22 in cancer stem cells (CSC) has been identified as a poor prognostic factor in multiple cancer models." (PMID 34660907, 2020). "USP22 plays an important role in AR protein stability and recruitment to AR-binding regions to drive AR driven cancer cell proliferation and tumor growth in CRPC cells." (PMID 34660907, 2020). "Frequent overexpression of USP22 protein was further discovered in various aggressive cancers including breast and colon cancers, and was demonstrated to be associated with poor prognosis of cancer patients." (PMID 31842906, 2019). "IHC analysis showed that USP22 was undetectable (scored as 0) in 33.2% (67/202), while USP22 levels in 17.8% (36/202), 27.7% (56/202), and 21.3% (43/202) of cancer cases were scored as 1+, 2+, 3+ respectively." (PMID 31842906, 2019).
cancer (continued). "Consistently, much more cleaved-PARP were found in USP22−/− cells (especially in USP22−/− H1299) than their parent cancer cells at 48 h post-irradition, indicating more apoptotic cancer cells were induced." (PMID 31842906, 2019). "In line with RNA-seq and Go analysis, Western blot analysis validated these changes in gene expression, and revealed a moderate increase of E-cadherin and/or decrease of Vimentin in USP22−/− cancer cells that reflects suppression of EMT singaling pathway." (PMID 31842906, 2019). "Consistently with above metastasis data, IHC analysis further uncovered that E-Cadherin protein were dramatically upregulated in USP22−/− cancer xenografts compared to the parent A549 cancer xenografts." (PMID 31842906, 2019). "We first measured the in vitro invasive potentials of A549 and H1299 cells upon USP22 knockout, and found that the migration and invasion of USP22−/− cancer cells were significantly decreased compared with their parent cells." (PMID 31842906, 2019). "The results showed that CD31 immunostainings were much lower in xenografts generated by USP22−/− cancer cells than their parent cancer cells, indicating that in vivo angiogenesis was dramatically suppressed upon USP22 knockout." (PMID 31842906, 2019). "Previous studies show that USP22 promotes proliferation and survival of anaplastic thyroid, hepatic, colorectal, and bladder cancer cells." (PMID 31689236, 2019). "Oncogenic roles of USP22 in cancers partially ascribes to its regulation on c-Myc oncogene transcriptional activity." (PMID 31842906, 2019). "Consistently, we herein identified that USP22 is drastically upregulated in A549 and H1299 cancer cells that survived cisplatin treatment, indicating an involvement of USP22 in cisplatin resistance and DNA damage repair." (PMID 31842906, 2019). "USP22 regulates transcription of genes related to epigenetic alterations and cancer progression by deubiquitination of H2A or H2B histones." (PMID 31689236, 2019). "In a separate experiment, we investigated the survival of NSG mice injected with USP22−/− and the parent A549 cancer cells." (PMID 31842906, 2019). "USP22 is highly expressed in several cancers, which considerably contributes to tumor recurrence, distant metastasis, therapeutic failure, and poor prognosis." (PMID 31689236, 2019). "Together, these findings suggest that USP22 is required for high level expression of HSP90AB1 protein levels both in human cancer cell lines in vitro as well as in murine epithelium and tumors in vivo." (PMID 31801945, 2019). "Using gene ontology (GO) enrichment analysis, we identified that angiogenesis, cell cycle progression, epithelial-mesenchymal transition (EMT), KRAS, and c-Myc signaling pathways were significantly downregulated in the USP22−/− cancer cells." (PMID 31842906, 2019). "One of crucial functions of USP22 in cancers is to transcriptionally regulate gene expression through modulating H2Bub1." (PMID 31842906, 2019). "We found that USP22−/− A549 and H1299 cancer cells generated much fewer and smaller colonies within 3 weeks compared to their parent cancer cells." (PMID 31842906, 2019). "In contrast, processes related to phosphorylation and tight junction were significantly upregulated in the two USP22−/− cancer cells." (PMID 31842906, 2019). "Apoptosis analysis showed that both 5 and 10 Gy irradiation induced more apoptosis at 48 h post-irradiation in both USP22−/− A549 and USP22−/− H1299 cancer cells than the parent A549 and H1299 cancer cells, respectively." (PMID 31842906, 2019). "Our findings support a direct role for USP22 as an essential component of the SAGA complex in promoting the expression of HSP90AB1 during cancer development and progression." (PMID 31801945, 2019). "Downregulation of USP22 reduces in vitro cancer cell proliferation, survival, migration, and invasion, and decreases in vivo tumor growth and metastasis." (PMID 31689236, 2019).